MIR32 (microRNA 32)
Synonyms: hsa-mir-32; MIRN32; miR-32; miRNA32
Gene: MicroRNA gene on chromosome 9 (109,046,229 to 109,046,298, reverse strand). Ensembl gene ENSG00000207698.
Gene Ontology:
Biological process: miRNA-mediated post-transcriptional gene silencing; Wnt signaling pathway
Cellular component: RISC complex
Homologues: Orthologues: chimpanzee ptr-mir-32 (100% identical), macaque MIR32 (100% identical), mouse Mir32 (100% identical), rabbit MIR32 (100% identical), guinea pig MIR32 (99% identical), pig ssc-mir-32 (99% identical), dog MIR32 (97% identical).
Diseases named in the same sentence as MIR32 in open-access papers:
MIR32 is named in the same sentence as 1 disease in open-access papers, as found by Europe PMC text mining. Sharing a sentence is not in itself a finding about the gene and the disease.
MIR32 shares sentences with these, for which no sentence is quoted: gastric cancer (1 paper).